VPS9D1 (VPS9 domain containing 1)
Synonyms: ATPBL; C16orf7; ATP-BL
Tractability: PROTAC: ubiquitination databases record sites on it; its protein half-life has been measured.
Gene: Protein-coding gene on chromosome 16 (89,707,128 to 89,721,324, reverse strand). Ensembl gene ENSG00000075399.
Subcellular location (Human Protein Atlas): Cytosol; Nucleoplasm
Gene Ontology:
Molecular function: identical protein binding; protein binding; small GTPase binding; guanyl-nucleotide exchange factor activity
Biological process: proton motive force-driven ATP synthesis; vesicle-mediated transport
Cellular component: cytosol; endocytic vesicle
Genetic constraint (gnomAD): Loss-of-function variants: 78 observed, 67.26 expected, observed/expected ratio (o/e) 1.16, 90% interval 0.96 to 1.4. The synonymous counts are far from expectation, so gnomAD's model fits this gene poorly and the ratio says little. Missense variants: 1,057 observed, 765.02 expected, observed/expected ratio (o/e) 1.38, 90% interval 1.31 to 1.45. Synonymous variants: 481 observed, 343.88 expected, observed/expected ratio (o/e) 1.4, 90% interval 1.3 to 1.51.
Homologues: Orthologues: chimpanzee VPS9D1 (99% identical), macaque VPS9D1 (97% identical), dog VPS9D1 (85% identical), mouse Vps9d1 (83% identical), pig VPS9D1 (83% identical), guinea pig VPS9D1 (83% identical), rat Vps9d1 (82% identical), rabbit VPS9D1 (65% identical), zebrafish vps9d1 (54% identical), tropical clawed frog vps9d1 (50% identical), Drosophila melanogaster spri (16% identical), Caenorhabditis elegans rin-1 (13% identical), and 2 more. Paralogues in human: RIN2 (17% identical), RIN3 (17% identical), RIN1 (16% identical), GAPVD1 (16% identical), RINL (12% identical), RABGEF1 (9% identical).
Diseases named in the same sentence as VPS9D1 in open-access papers:
VPS9D1 is named in the same sentence as 2 diseases in open-access papers, as found by Europe PMC text mining. Sharing a sentence is not in itself a finding about the gene and the disease. The quoted sentences say what the papers report.
pancreatic cancer (1 paper, 2019). "For instance, PDX1 was involved in both CASC8-related and VPS9D1-related networks, and also recognized as a key regulator and a potential target in pancreatic cancer." (PMID 31720124, 2019).
Sepsis (1 paper, 2014). Sepsis is defined as life-threatening organ dysfunction caused by a dysregulated host response to infection. "One gene, Vacuolar Protein Sorting 9 Domain-containing gene 1 (VPS9D1), showed significant associations between potentially functional mRNA variants and sepsis survival." (PMID 25538794, 2014). "VPS9D1 (transcript NM_004913) variants were significantly associated with sepsis outcomes as measured by Fisher’s binary (−log10P value 4.48, FDR = 0.07, odds ratio 0.08) and regression (−log10P value 5.03, FDR = 0.01, odds ratio 0.09)." (PMID 25538794, 2014). "VPS9D1, whose expression was increased in sepsis survivors, had a higher burden of missense variants in sepsis survivors." (PMID 25538794, 2014). "The association of sepsis survival with a robust immune response and the presence of missense variants in VPS9D1 warrants replication and further functional studies." (PMID 25538794, 2014). "Potentially functional variants in Vacuolar Protein Sorting 9 Domain-containing gene 1 (VPS9D1) were associated with sepsis outcome." (PMID 25538794, 2014). "However, VPS9D1 contained variants that were significantly more likely to occur in sepsis survivors." (PMID 25538794, 2014). "Indeed, we observed the presence of expressed sequence variants in VPS9D1 to be associated with sepsis survival." (PMID 25538794, 2014). "Moreover, expressed sequence variants in VPS9D1 were significantly associated with sepsis outcomes." (PMID 25538794, 2014). "VPS9D1 has also been shown to interact with GRB2 (growth factor receptor-bound factor 2), which was also more highly expressed in sepsis survivors and in those with VPS9D1 variants." (PMID 25538794, 2014). "Forty-four VPS9D1 variants were identified in sepsis survivors and two variants in sepsis non-survivors." (PMID 25538794, 2014). "Although expression of VPS9D1 was significantly decreased in sepsis non-survivors, this did not markedly decrease the number of comparisons between nucleotide variants and sepsis outcomes." (PMID 25538794, 2014). "VPS9D1 expression was significantly higher in sepsis survivors than in sepsis non-survivors." (PMID 25538794, 2014).